AFP (alpha fetoprotein)
Diseases named in the same sentence as AFP in open-access papers (continued):
Sharing a sentence is not in itself a finding about the gene and the disease.
tumor (continued). "Among patients with tumor size > 3 cm, multivariate Cox analysis showed that serum AFP > 20 ng/mL (HR: 1.680, 95% CI: 1.233–2.290, p = 0.001) and ALBI grade 2–3 (HR: 1.725, 95% CI: 1.247–2.386, p = 0.001) were associated with decreased overall survival." (PMID 36077743, 2022). "The formula for the weighted value is: Y = 0.693 × [maximum tumor diameter] + 0.961 × [tumor margin + 0.652 × [direct bilirubin] + 0.736 × [AFP] – 5.859." (PMID 36577952, 2022). "When it was combined with a clinical model, consisting of tumor size and alpha-fetoprotein (AFP), the combined model (AP+HBP+Clin_model) showed an area under the curve of 0.90 and 0.70 in the training and test subsets, respectively." (PMID 35664790, 2022). "As one of the earliest tumor markers to be found, alpha-fetoprotein (AFP) has been routinely employed in a variety of HCC surveillance and detection procedures for decades." (PMID 35624643, 2022). "DC-derived EVs are able to stimulate tumor-specific immune responses when loaded with TAAs (e.g., melanoma-associated antigen 3-MAGE-A3, alpha-fetoprotein-AFP) or IFN-γ." (PMID 36498469, 2022). "From the prognostic point of view, the new staging has introduced alpha-fetoprotein (AFP) values as a relevant prognostic factor in it from tumor size." (PMID 36624801, 2022). "Chi-square showed that ZNF334 was related to tumor growth-related indicators-alpha-fetoprotein (AFP), number of tumors and tumor capsule, and was also concerned with metastasis-related indicators-portal vein tumor thrombus." (PMID 35534462, 2022). "In the analysis of serum tumor markers, result showed that the AFP level of HCC patients was obviously increased than that of the control group, CHB and LC groups, and the difference was statistically significant." (PMID 34825738, 2022). "Despite this transient reduction of AFP, a durable reduction in total tumour burden was observed through computed tomography (CT) imaging ~2 months after receiving the 7th mRNA HBV-TCR T-cell infusion." (PMID 35919490, 2022). "The PROSASH-II model, which comprised albumin, bilirubin, vascular invasion, extrahepatic spread, tumor size and AFP, has been shown to have good discriminative value in predicting the survival of patients with HCC receiving sorafenib treatment." (PMID 35454919, 2022). "Tumor size, tumor number, histological grade, and AFP were all shown to have significant correlations with MVI based on the univariate analyses of clinicopathological characteristics between the MVI-positive and negative patient groups." (PMID 36684226, 2022). "Patients with recurrence were likely to have larger maximal tumor size, tumor count, and higher AFP concentration." (PMID 35936699, 2022). "Further analysis indicated that the high-ratio group was associated with a higher AFP level (>400 ng/ml), an MVI-positive status, multiple tumors, and a smaller tumor diameter (median = 4 cm) in comparison to the low-ratio group." (PMID 35936682, 2022). "(E) The association between the optimal signature and multiple clinical features, including BCLC and TNM stage, tumor thrombus, AFP level, and histologic grade." (PMID 35191375, 2022). "Propensity score matching (PSM) was used to balance the baseline characteristics, including age, sex, serum alpha-fetoprotein levels, Child–Pugh class, tumor size, and tumor stage." (PMID 35337274, 2022). "Because AFP antibodies enhance the cellular uptake of micelles, chemotherapeutic agents encapsulated in the core of micelles are released to kill tumor cells." (PMID 35624643, 2022). "Univariate Cox proportional hazards regression models showed that disease stage, relapse, maximum tumor diameter, and AFP returning to normal within 2 months postoperatively were risk factors affecting patient survival." (PMID 36601033, 2022).
tumor (continued). "Univariate analysis indicated that hepatic reserves (Child–Pugh classes and ALBI grades), tumor stages (UICC and BCLC stages), and tumor markers (DKK-1, AFP, and PIVKA-II levels) were risk factors for poor survival outcomes." (PMID 35269944, 2022). "In this study, the TACE group had heavier tumor burden and higher AFP levels than the GKR group before PSM." (PMID 35729469, 2022). "AFP is a specific tumor marker for HCC, and the level of the tumor marker was elevated in four patients." (PMID 36698409, 2022). "Our group has established a dynamic selection process based on three variables (AFP, response to locoregional therapy, waiting time >6 months) reflecting tumor biology, when extrahepatic disease and macrovascular invasion was excluded." (PMID 35681642, 2022). "The most common clinical tumor markers used to diagnose HCC are alpha-fetoprotein (AFP) and carcinoembryonic antigen (CEA)." (PMID 36147735, 2022). "Tumor biology represented by tumor number and size are strongly prognostic for OS and DFS while AFP is significantly associated with DFS only." (PMID 35227234, 2022). "Univariate logistic regression analysis for categorical variables showed that AFP (p < 0.001), tumor size (p < 0.001), and TNM stage (p = 0.03) were potential risk factors for the presence of MVI (data not shown)." (PMID 35310437, 2022). "In a retrospective review of 125 patients with elevated preoperative AFP (>20 ng/mL) undergoing liver transplant, patients who had rapid AFP normalization within one-month post-transplant had less tumor recurrence." (PMID 36290870, 2022). "Intriguingly, a positive correlation exists between CPI and AFP, and the latter is a biomarker for tumor genesis and cancer progression in HCC." (PMID 36408192, 2022). "AFP-based vaccines were used in earlier trials and have since expanded to other tumor antigens such as GPC3 and hTERT." (PMID 35433430, 2022). "The logistic regression analysis showed that the EXO1 expression levels positively correlated with T stage, tumor status, histologic grade, and AFP levels in the HCC tissues." (PMID 35769911, 2022). "Given the increased level of serum MRPL9 in HCC patients, we further determined the correlation between MRPL9 and different clinicopathological factors, including gender, age, tumor size, CNLC stage and HCC diagnostic markers including AFP, Ferritin." (PMID 36684217, 2022). "In short, in the current real clinical environment, it is generally believed that tumor size, clinical stage, tumor invasion extent, treatment regimen and AFP level are closely related to the prognosis of patients." (PMID 36358825, 2022). "Tumor markers, such as AFP, β-HCG, and LDH, were normal in all patients before surgery except 2 patients with increased LDH levels." (PMID 35712094, 2022). "From the perspective of liver function indexes and tumor markers, lnc-MAFG-AS1 expression was associated with an abnormal alpha-fetoprotein (AFP) level (p = 0.004)." (PMID 36034393, 2022). "Tumor markers revealed elevated alpha-fetoprotein (AFP) levels (7.03 ng/ml) and des-gamma-carboxy prothrombin (DCP) levels (33.0 mAU/ml)." (PMID 36698409, 2022). "In this study, some tumor factors (high level of AFP, large tumor size, multiple tumors, and intrahepatic metastasis) showed significant differences between patients with severe PHLF and without severe PHLF." (PMID 35918753, 2022). "Regarding early tumor marker responses, early AFP reduction (p = 0.017) and DCP reduction (p = 0.032) were significantly associated with the ORR; however, their associations with survival outcomes were insignificant." (PMID 35997637, 2022). "Alpha-fetoprotein (AFP), alpha-L-fucosidase (AFU), arginase-1(Arg-1) are promising diagnostic tumor markers of HCC, and their measurements increased the detection sensitivity and specificity for HCC." (PMID 35081125, 2022).
tumor (continued). "The multivariate analysis showed that tumor size, age, pathological grade, AFP, radiation, AJCC stages, chemotherapy and surgery (P<0.05) were independent prognostic factors for CSS which were included in the nomogram." (PMID 36185206, 2022). "Next, CpGf-CMV-sr39 and CpGf-AFP-sr39 were administered to tumor-bearing mice to probe sr39 expression in vivo using these two vectors." (PMID 35857843, 2022). "The univariate Cox analysis revealed that age, HBsAg, platelet, TBil, AST, AFP, tumor size, tumor number, MVI, satellitosis, BCLC staging, and tumor differentiation were potential risk factors of HCC early recurrence." (PMID 35686100, 2022). "Primary tumor burden and the HCC biomarker, a-fetoprotein (AFP), have been the only factors linked to response to LDT." (PMID 34689234, 2022). "Unsurprisingly, patients in MVI and PVTT groups exhibited higher AFP level, larger tumor size and poorer histological grade than the control group." (PMID 36203429, 2022). "Parameters to assess the indication for radioembolization include determination of tumour load, volume and serum tumour markers (e.g. alpha-fetoprotein (AFP), carcinoembryonic antigen (CEA))." (PMID 35146577, 2022). "When considering categorical variables with tumor size > 3 cm and AFP level > 200 ng/ml, univariable and multivariable analysis of baseline characteristics associated with aggressive intra-segmental recurrence showed the same results." (PMID 36333426, 2022). "Multivariate Cox regression analysis indicated that AFP, APRI, MVI, number of tumours, tumour diameter and PVTT were independent risk factors for RFS; female and ALT were independent protective factors for RFS." (PMID 35255845, 2022). "Tumor markers AFP, b-HCG, and CA-125 were normal; therefore, the rare growing teratoma syndrome (GTS) was feared as a severe outcome." (PMID 36556917, 2022). "The miR-106b-5p expression level was positively correlated with α-fetoprotein (AFP), hepatitis B surface antigen (HBsAg), and tumor size." (PMID 35342408, 2022). "The multivariate analysis revealed that GNRI < 98, tumor size ≥ 5cm, tumor number ≥ 2, alpha-fetoprotein level ≥ 400 and TACE times < 3 were independent predictors of a poor OS." (PMID 36595771, 2022). "It has been observed that three tumour markers (AFP, CA 125 and fPSA) are appropriate for all lists, and the remaining parameters do not exceed the limits of guidelines, except for the RCPA recommendations." (PMID 35966261, 2022). "After adding postoperative features, microvascular invasion and tumor differentiation were additional significant variables in lieu of corona enhancement and AFP level." (PMID 35554652, 2022). "Lab tests demonstrated elevated levels of blood tumor markers, including alpha-fetoprotein (AFP), carcinoembryonic antigen (CEA) and neuron-specific enolase (NSE)." (PMID 35860547, 2022). "As well known, levels of AFP, tumor grade, or vascular invasion are the prognostic indictors of HCC." (PMID 35859724, 2022). "The tumor size was 0.9 cm, 7.5 cm, and 9.7 cm for the three patients with normal AFP levels, whereas the mean tumor size was 7.4 cm (range, 3.1-14 cm) in the other seven patients." (PMID 36568193, 2022). "In 2012, a multicentre French study incorporated an AFP threshold, the number of nodules, and the largest tumor diameter into a prognostic score." (PMID 35965558, 2022). "The Munich-TACE score (M-TACE) uses the values of bilirubin, international normalized ratio, C-reactive protein, creatinine, and AFP, as well as tumor extension (size and number of nodules, vascular invasion, metastasis) to divide patients in three subgroups." (PMID 35330436, 2022). "The SPINK1 and SPINK1+AFP models exhibited a higher discriminatory efficacy than did AFP alone in stage I and II tumor samples: AUC = 0.72:0.72:0.53, specificity = 92.0%:92.4%:90.6%, sensitivity = 46.9%:45.7%:23.4%." (PMID 35924241, 2022).
tumor (continued). "We next evaluated the prognostic impact of the GNRI depending on the tumor stage and alpha-fetoprotein (AFP) level." (PMID 36595771, 2022). "We reviewed outcomes in patients who met the University of California San Francisco (UCSF) criteria (n = 159) and our center-specific criteria (UCSF+) (largest tumor diameter ≤ 10 cm, any tumor number, AFP ≤ 1000 ng/ml) (n = 58)." (PMID 34117916, 2022). "Univariate Cox regression showed that body mass index (BMI), AFP of > 1000 ng/mL, tumor numbers, maximal tumor diameter, a sum of tumor diameters, and TNM stage were the risk factors for HCC recurrence." (PMID 35936699, 2022). "The HAP score integrated tumor size, AFP, bilirubin, and albumin together, and the three modified HAP series scores (mHAP, mHAP-II, and mHAP-III) were subsequently developed through various adjustments subsequently." (PMID 36776366, 2022). "Although serial serum AFP levels were monitored before each cycle of chemotherapy, a final pathologic diagnosis on biopsy is more straightforward to evaluate tumor response." (PMID 36452350, 2022). "For the postoperative Cox model, MVI and poor tumor differentiation were additional significant parameters included, whereas corona enhancement and AFP level > 400 ng/mL were excluded." (PMID 35554652, 2022). "This study aims to assess the correlation between serum levels of alpha-fetoprotein and tumour dimensions in patients diagnosed with HCC, that were previously treated with direct-acting antivirals for hepatitis C viral infection." (PMID 35497085, 2022). "Since all proposed models are based on adjustment of probabilities, decreasing upper limits of AFP levels should be considered with increasing tumor burden to maintain the rate of futile downstaging and/or LT approaches within accepted limits." (PMID 35529597, 2022). "Preoperative AFP level has been accepted as one of the tumor biological indicators to predict tumor recurrence and select patients for LT." (PMID 36203429, 2022). "In the patients receiving TACE (n = 799), the platelet count (≥100 × 109/L), AFP (≥400 ng/mL), tumor size, MVI, ALBI grade (Model 1), and mALBI grade (Model 2) were independent predictors of OS in the multivariable Cox regression analysis." (PMID 36291867, 2022). "Using prognostic indicators, including tumor size, tumor number, histological grade, and AFP, we built a nomogram to predict MVI." (PMID 36684226, 2022). "and HBsAg positivity, AFP level ≥400 ng/ml, invasion of the liver capsule, and tumor number ≥2 were independent prognostic factors for recurrence, whereas HBsAg positivity was an independent risk factor of overall survival." (PMID 36420403, 2022). "Overexpression of TTK is associated with high serum AFP (alpha-fetoprotein) levels, large tumor size, advanced TNM stage (tumor, nodes, and metastases), and distant metastases." (PMID 36405310, 2022). "Serum AFP level mainly reflects the pathological conditions and tumor activity, while IINS reflects the overall status of the patient, including inflammation, immune, and nutritional status." (PMID 36016629, 2022). "In 2019, ramucirumab, a monoclonal antibody targeting the VEGF receptor 2, was approved for patients with tumor progression under sorafenib and elevated alpha-fetoprotein (AFP ≥ 400 ng/mL)." (PMID 35454881, 2022). "Univariate analysis of baseline clinical and pathological characteristics showed that larger tumor sizes, higher AFP levels, challenging tumor locations, smaller MAM and higher ALBI stage were more frequently observed in patients with ER." (PMID 36042507, 2022). "Tumor characteristics, including pre-transplant alpha-fetoprotein (AFP), viable tumor number, microvascular invasion, differentiation, and maximum tumor size were comparable between the two groups." (PMID 36171260, 2022). "The novel criterion (a-RECIST) is based on RECIST 1.1 combining with the percentage change of AFP (AFPΔ) for identifying tumor response of conversion-radiotherapy for uHCC patients before hepatectomy." (PMID 35686094, 2022).
tumor (continued). "The high-repair group displayed significantly higher expression of cell cycle and hepatoblast marker AFP than the low-repair group and tumor-adjacent normal tissues (p < 0.001 for all pairwise comparisons)." (PMID 36077818, 2022). "The SNRPD1 protein expression level was significantly correlated to Age (P=0.049), TNM staging (P=0.010), Serum AFP level (P=0.001), Tumor differentiation (P=0.002), Vascular invasion (P=0.006), Recurrence (P=0.036), and Survival (P=0.025)." (PMID 34976182, 2022). "Clinical diagnosis and staging of IGs are based on symptoms, tumor markers such as α-fetoprotein (AFP) or β-human chorionic gonadotropin (HCG) in serum and cerebrospinal fluid (CSF), and brain and spinal magnetic resonance imaging (MRI)." (PMID 35130327, 2022). "The univariate analysis suggested that MVI, recurrence time, tumor size, tumor number, extra-hepatic metastasis, AFP > 400 ng/mL, and PLR were significant factors." (PMID 35585534, 2022). "In particular, in the association between tumor‐related factors, which have been reported to be associated with prognosis, and the ALBI grade and Child‐Pugh score, AFP was higher in patients with ALBI grade 2 than those with grade 1 (P = .0029)." (PMID 35106423, 2022). "Unfortunately, the presence of an AFP-specific T cell response at 4W post-ablation indicated a rapid tumor progression (P=0.009)." (PMID 36618423, 2022). "The OS achieved with tumor size cutoff of 10 cm and AFP < 1000 ng/ml was comparable to UCSF, Toronto, and Hangzhou criteria." (PMID 34117916, 2022). "In any case, particular caution must be taken in the treatment of periportal HCC with larger tumor size or AFP ≥ 400 ng/ml for ablation." (PMID 34983650, 2022). "Our finding has clinical implications in that while Child–Turcotte–Pugh class and alpha-fetoprotein level are patient or tumor-related factors that physicians cannot change, LD-CCRT is a factor we can modulate." (PMID 35626001, 2022). "Tumor markers such as AFP, CA 125, CEA, and CA 19-9 are in the usual range in these patients and wouldn't aid us in diagnosis and follow up." (PMID 35468380, 2022). "Based on ROC curve analysis, we determined the best threshold values for maximum tumor diameter, direct bilirubin, and AFP to be 50 mm, 2.7 μmol/L, and 360.7 ng/mL, respectively." (PMID 36577952, 2022). "LAIR-1+Tc% was correlated with the HCC surrogate tumor marker AFP (r = 0.367, p = 0.001) and insulin resistance and inflammation prognostic ratios/indices." (PMID 36293412, 2022). "Tumor markers such as CEA, AFP, CA15-3, and CA19-9 have very limited diagnostic value for HSC, and are positive indicators in a small number of patients." (PMID 35945746, 2022). "The secondary goal is to compare the general results of LT in terms of tumor recurrence, dropout rate, overall survival and disease-free survival before and after the AFP model implementation." (PMID 34069594, 2021). "The member SKA1 was associated with alphafetoprotein (AFP), tumor size, and the TNM stage in patients with HCC and proliferation, the clinical stage and lymph node metastasis in NSCLC." (PMID 35095717, 2021). "Orthotopic tumor establishment was confirmed with serum AFP measurement and IVIS bioluminescence imaging six weeks after subcapsular HepG2 cell injection." (PMID 33580090, 2021). "High or increasing serum AFP and AFP-L3 levels have been shown to be indicative of large tumor size, advanced stage, and extra-hepatic metastasis in HCC." (PMID 33562077, 2021). "SORD levels have the advantage of predicting prognosis as well as reflecting hepatic functional reserve compared with other conventional tumor markers such as AFP and PIVKA-II." (PMID 34885252, 2021).